CRP (C-reactive protein)
Diseases named in the same sentence as CRP in open-access papers (continued):
Sharing a sentence is not in itself a finding about the gene and the disease.
infection (continued). "C-reactive protein (CRP), white blood cell (WBC) and absolute neutrophil counts (ANC) are important inflammatory biomarkers in the early diagnosis of infections." (PMID 28451028, 2017). "C-reactive protein (CRP) is a cytokine-induced acute phase protein and biomarker of inflammation and infection." (PMID 27386859, 2016). "We therefore compared the predictive value of the ICIS with that of the white blood cell count (WBC), C-reactive protein (CRP) and procalcitonin (PCT) for infection and its severity in critically ill patients." (PMID 27384242, 2016). "In AS patients with Vit D deficiency, SAA correlated directly with the disease activity (BASDAI) but also with infection/ inflammatory markers (Neu number, ESR, CRP and Fb)." (PMID 27713770, 2016). "We therefore performed a prospective study on the predictive value of ICIS for probable or proven infection in critically ill patients with suspected infection, and compared its performance with that of the white blood cell count (WBC), CRP and PCT levels." (PMID 27384242, 2016). "A rise in serum concentration of C-reactive protein (CRP) generally is related to trauma, inflammation or infection." (PMID 27112583, 2016). "Inflammatory markers such as C-reactive protein (CRP) and procalcitonin can assist in diagnosing serious infections in hospital settings." (PMID 27716201, 2016). "In the bacterial infection group, the performance of PCT, CRP and WBC levels in the diagnosis of neonatal infection before antibiotic treatment, i.e., in the early stage of infection, was evaluated using ROC." (PMID 28083019, 2016). "The patients were then evaluated based on the reactivation of infection, the Harris hip score system, X-ray, ESR, and CRP." (PMID 27029638, 2016). "C-reactive protein (CRP) is an inflammatory marker produced by the liver in response to interleukin-6 and its serum levels increase as a consequence of trauma or infection." (PMID 27843647, 2016). "The area under the receiver-operating characteristic (ROC) for diagnosis of infection was 0.75 for PCT (p = 0.001), 0.63 for CRP (p = 0.09) and 0.52 for sTREM-1 (p = 0.79)." (PMID 27096761, 2016). "CRP and PCT kinetics from the pre-VAP period to the diagnosis of the infection were analyzed and compared between the two groups." (PMID 27256282, 2016). "C-reactive protein (CRP), an acute-phase protein, is known as a useful biomarker in detecting infections postoperatively." (PMID 25585544, 2015). "Despite having incomplete preoperative inflammatory marker testing, we have also shown that there still remain a significant number of patients who are likely to have occult infection at revision for aseptic loosening despite normal preoperative ESR and CRP." (PMID 26583149, 2015). "Although it has been suggested that elevated CRP levels can be used as a predictor of active infection in SLE patients with a high specificity, CRP levels during SLE flares can range widely in the number." (PMID 26798529, 2015). "Decision for second-stage reimplantation is made after a minimum 2-week antibiotic-free interval, when clinical signs of infection have subsided and ESR and CRP levels have steadily trended toward to normal." (PMID 24821631, 2015). "Antibiotic administration was started whenever their APR scores were 3 points, indicative of an infectious state, or 2 points due to being CRP- and AGP-positive, and was continued until the infections had resolved." (PMID 25667565, 2015). "MPV, platelet distribution width (PDW) platelet count, and other infection markers (white blood cell [WBC] count, erythrocyte sedimentation rate [ESR], and C-reactive protein [CRP]) were measured." (PMID 26666588, 2015). "When selecting the 20 most used diagnoses, we found that respiratory diseases, infections and fever constituted 50 % and 59 % of all contacts at daytime and OOH, respectively, and a CRP test was used in 44 % and 58 % of the consultations." (PMID 26585447, 2015).
infection (continued). "The reduction rates of the median CRP and PCT levels during the whole infection period were 82.0% and almost 100.0%, respectively." (PMID 25894539, 2015). "Normal CRP and ESR were helpful to exclude infection, but when elevated, had poor positive predictive values." (PMID 26181332, 2015). "Serum endocan, C-reactive protein (CRP), and procalcitonin (PCT) levels during four periods during infection were measured (day 0, day 1-2, day 3-5, and day 6-10)." (PMID 25894539, 2015). "Further, when combined with the CRP level, it is useful to evaluate disease activity in SLE patients with infection." (PMID 26273660, 2015). "Chez les patients présentant un taux sérique de CRP élevé, les scores de gravité (APACHE et SOFA), le pourcentage de patients présentant une infection et la durée du séjour en réanimation sont plus élevés." (PMID 26301005, 2015). "An elevated serum C-reactive protein (CRP) level >40 mg/L was noted in a substantial proportion of the patients in the CA6 and CA10 infection groups." (PMID 26398767, 2015). "Serum total superoxide dismutase (SOD) activity, malondialdehyde (MDA) level, tumor necrosis factor alpha (TNF-α), C-reactive protein (CRP) and interleukin-1 beta (IL-1β) levels were measured at 5, 10, 15, 20 days post infection (dpi)." (PMID 25723390, 2015). "The aim was to evaluate the usefulness of inflammatory markers including C-reactive protein (CRP) and the neutrophil-to-lymphocyte ratio (NLR) for diagnosis of infection and predicting the outcomes in hospitalized cirrhotic patients." (PMID 26498833, 2015). "Both CRP and PCT as a single biomarker are more specific for bacterial etiology of infection at high concentrations, but lower concentrations of CRP and PCT are often observed during both viral and bacterial infections." (PMID 26672961, 2015). "C-reactive protein (CRP) is a plasma protein that rises rapidly in the circulation in response to acute inflammation, infection, and tissue damage." (PMID 26380255, 2015). "C-reactive protein (CRP) is a major acute phase protein showing increasing serum concentrations in dogs with systemic inflammation following e.g., surgery, trauma, infections, or neoplasia." (PMID 26483038, 2015). "The low specificity and modest positive predictive value calculated from the AUROC suggest that the use of an elevated CRP alone as an indicator of developing complications post-esophagectomy may lead to antibiotic overtreatment, amongst others, if considered specific for infection." (PMID 25663633, 2015). "Bacterial-induced host proteins such as procalcitonin, C-reactive protein (CRP), and Interleukin-6, are routinely used to support diagnosis of infection." (PMID 25785720, 2015). "Increases in C-reactive protein (CRP) and white blood cell (WBC) counts after orthopedic surgical procedures can give evidence of postoperative infection." (PMID 25585544, 2015). "After a major elective surgical insult both CRP and PCT serum levels increased independently of the presence of infection." (PMID 25132018, 2014). "It is well known that after of the presence a major elective surgical insult both CRP and PCT serum levels markedly increased independently of infection." (PMID 25132018, 2014). "However, CRP-deficient mice were not more susceptible to infection with pneumococcal strains RF206, serotype 1, and RF32, serotype 19F, mucoid colonies of heavily capsulated organisms isolated from blood cultures; or strain Tz1003-2, serotype 6A, isolated from a carrier." (PMID 24673624, 2014). "Because the CRP is synthesized in the hepatic cells within 6-to-8 hours after infection and thereafter the peak of CRP concentrations exists in the circulation between 36 and 50 hours, there may be a gap between increased serum CRP levels and infectious states." (PMID 25548797, 2014). "Both CRP and PCT showed significant correlation with infection severity using Spearman correlation (CRP: P <0.001, r = 0.378; PCT: P <0.001, r = 0.414)." (PMID 25407928, 2014).
infection (continued). "In present study, early response of CRP, Hp, SAA, and Pig-MAP induced by IN and IT infection with SwH3N2 virus was characterized and compared, during the first 10 dpi." (PMID 24734294, 2014). "We suggest that CRP levels of 10–15 mg/L were due to OC, higher-than-normal LGI, or mild asymptomatic infections." (PMID 24516611, 2014). "Although PCT sensitivity and specificity are considered to be less strong than ESR or CRP to indicate IDFU, this study showed that PCT, like other inflammatory markers, can prove helpful in diagnosing the infection." (PMID 24696696, 2014). "Accuracy of CRP is lower than for PCT, whereas the eosinophil count and cf-DNA serum levels cannot be recommended as indicators of infection in patients with SIRS." (PMID 24903083, 2014). "The CRP levels predicted the infection in general on POD 6–7, one-day earlier, than the (median) day of post operative infection diagnosis." (PMID 25132018, 2014). "We investigated the alteration of CRP, WBC, neutrophil count, suPAR levels, CD4+ CD25high Tregs, CD64+ and CD177+ neutrophils and monocytes in 12 acute ischemic stroke patients free of infection within 6 hours and one week after the insult." (PMID 24597828, 2014). "According to their reports, PCT indicates infection more reliably than traditional indicators such as body temperature, WBC, CRP, or cytokines (IL-6, IL-8)." (PMID 25960877, 2014). "CRP and SAA were significantly induced at the very early stage of infection (from 1 to 2 and 3 dpi, respectively)." (PMID 24846450, 2014). "Serum CRP and PCT are two unspecific serologic markers of inflammation and infection that, in our group of uncomplicated THA patients, increased differently, but with similar trend, in the postoperative days." (PMID 24877114, 2014). "Sub-analyses of CRP and PCT based on renal function showed that both markers were significantly elevated in patients with infection." (PMID 25407928, 2014). "C-reactive protein (CRP) is a classical plasma protein marker that is markedly elevated in the acute phase of inflammation, infection, and tissue damage and thus has been broadly used for monitoring and differential diagnosis." (PMID 24872601, 2014). "We compared routine measurements of procalcitonin (PCT), C-reactive protein (CRP), white blood cell count (WBC) and temperature in the detection of ICU-acquired infections." (PMID 23547830, 2013). "PCT, CRP, WBC and temperature progression from day −4 (D-4) to day 0 (D0) (day of infection diagnosis or ICU discharge) was analysed." (PMID 23547830, 2013). "The five clinical parameters, IG#, CRP, LBP, IL-6 and SOFA score were analyzed for their discriminative power to diagnose infection." (PMID 23398965, 2013). "The C-reactive protein (CRP) levels on the first and second postoperative days were significantly greater in the infection group (p = 0.02 and p = 0.05, respectively)." (PMID 23819455, 2013). "Laboratory parameters in use for the rapid identification of infection include procalcitonin (PCT), interleukin 6 (IL-6), lipopolysaccharide binding protein (LBP), and CRP." (PMID 24349403, 2013). "Therefore, DHAV-C infection could promote a disturbance in CRP production." (PMID 23923051, 2013). "In older children and adults, serum/plasma levels of C-reactive protein (CRP), IgG and IgG subclass have proved useful indicators of infection and inflammation." (PMID 23941472, 2013). "Vitamin A status and current infection was assessed by an ELISA measuring retinol-binding protein (RBP) and C-reactive protein (CRP)." (PMID 23442248, 2013). "Furthermore, our study suggests that a combination of weekly weight measurements, CRP and X-rays combined with biweekly injections of calcium-binding fluorophores and post-mortem bacterial bone culture provide the most optimal insight into infection development and status." (PMID 24188807, 2013). "Exposure to multiple pathogens resulted in the strongest CRP, Hp and SAA response as compared to mono-infection with SIV or Pm." (PMID 23332090, 2013).
infection (continued). "“Old” markers like CRP, WBC count and neutrophil count are still the most frequently used infection markers in daily clinical practice." (PMID 23049706, 2012). "Eight variables were assessed for significant covariate effects on the outcomes, including age, sex, the C282Y/H63D genotype, CagA strain infection status, and natural log of CEA, CRP, GGT, and ALT." (PMID 22761678, 2012). "PSP/reg performed better than CRP and PCT, which are widely used to diagnose infection but which, owing to their poor accuracy in this indication, should not be used to predict disease outcome." (PMID 22748193, 2012). "Biomarkers of infection, namely C-reactive protein and procalcitonin (PCT), are potentially useful in the diagnosis of infection as well as in the assessment of its response to antibiotic therapy." (PMID 22824162, 2012). "Circulating concentrations of lymphotactin, MIP-1γ, MPO, MMP9, as well as VCAM-1, CRP, SAP, and haptoglobin were altered with Hb-infection and reduced in Hb-infected mice treated with anti-IL-7Rα M595." (PMID 23057802, 2012). "Laboratory studies should include C-reactive protein (CRP), erythrocyte sedimentation rate (ESR), and complete blood count with differential if infection is suspected." (PMID 23304084, 2012). "The predictive value of copeptin in respect of SAI was similar to that of established biomarkers of infection (i.e. WBC, CRP)." (PMID 23118979, 2012). "Additional predictors of an elevated CRP were a history of CAD (P < 0.001), female sex (P = 0.04), and the presence of infection (P = 0.02)." (PMID 22121485, 2012). "Biomarkers of infection, namely CRP and PCT, are potentially very useful in the diagnosis of infection as well as in the assessment of its response to antibiotic therapy." (PMID 22824162, 2012). "C-reactive protein (CRP) is an extremely sensitive objective marker of inflammation, tissue damage, and infection." (PMID 21272380, 2011). "If there is a question of a postoperative infection, the use of successive erythrocyte sedimentation rate (ESR) and CRP studies has proven useful along with enhanced magnetic resonance imaging scans." (PMID 21427784, 2011). "Currently, one can perhaps consider C-reactive protein (CRP) and procalcitonin (PCT) the most popular biomarkers of infection." (PMID 22758612, 2011). "In multivariate Cox regression analyses for variables obtained at ICU admission including CRP and PCT as markers of inflammation and infection, NT-proCNP remained an independent significant prognostic parameter." (PMID 21281508, 2011). "Serum C reactive protein (CRP) was an acute-phase protein synthesized by the liver following stimulus by various cytokines, markedly increased within hours after infection or inflammation." (PMID 21714897, 2011). "Traditional infection markers such as the white blood cell (WBC) count, neutrophil count and C-reactive protein (CRP) level are of limited value in the early detection of community-acquired bacteremia." (PMID 21034463, 2010). "The average CRP and white cell count (WCC) at time of infection presentation was 6.3±5.5 mg/L and 11.1±3.3×103 mL respectively; the average CRP and WCC after VAC applications and antibiotics treatment dropped to 1.1±1.4 mg/L and 7.2±3.2×103 mL respectively." (PMID 20419005, 2010). "We prospectively evaluated the validity of CRP and PCT to diagnose infection in patients receiving ATG prior to hematopoietic stem cell transplantation." (PMID 19291300, 2009). "C-reactive protein (CRP) is an acute-phase protein that is predominantly synthesized by hepatocytes in response to inflammation, infection, and tissue damage." (PMID 19503785, 2009). "C-reactive protein (CRP) is the prototype of acute phase proteins’ family, which increases in response to infection, trauma, burning, tissue infarction, inflammation and tumours." (PMID 27956962, 2009).
infection (continued). "Under either infection-inflammation or normal condition, the addition of increasing amounts of L-ficolin to a fixed concentration of C1q did not dissociate C1q from CRP and vice versa indicating that C1q and L-ficolin might bind to different domains of the CRP molecule." (PMID 19180241, 2009). "Biochemical markers of inflammation – C-reactive protein (CRP) and procalcitonin (PCT) – were shown to be able to reliably diagnose infection in the general population." (PMID 19291300, 2009). "Thus understanding the genetic background of CRP that regulates basal but also by infection or any type of inflammation-induced concentration of CRP might contribute to stratification of healthy subjects to different groups with higher or lower degree of cardiovascular disease development." (PMID 19639050, 2009). "C-reactive protein (CRP) is an acute-phase reactant that is produced in response to acute injury, infection or other inflammation stimuli." (PMID 19032759, 2008). "Many authors target finding proinflammatory markers of infection and SIRS other than the CRP, such as PCT, IL-1, IL-6, or TNFα." (PMID 17598889, 2007). "Previous studies comparing groups of patients who received antibiotics because of documented vs. suspected infection, already evaluated serum concentrations of CRP and/or WCC counts in the diagnosis of infection." (PMID 17868441, 2007). "The NNIS score and the evolution of serum IL-6 and various acute-phase proteins (C-reactive protein [CRP], albumin, prealbumin and transferrin) were correlated with postoperative infections and length of hospital stay (LOS)." (PMID 17505683, 2007). "The progression of CRP, temperature and WCC from day -5 to day 0 (day of infection diagnosis or of ICU discharge) was analyzed." (PMID 16635270, 2006). "Our aim was to assess the value of daily measurements of C-reactive protein (CRP), temperature and white cell count (WCC) in the early identification of intensive care unit (ICU)-acquired infections." (PMID 16635270, 2006). "The plot demonstrates that high bp-SUVr values were found even in patients without infection and with low CRP, especially in the neoplasia and other groups." (PMID 41594176, 2026). "CRP levels increased after 6 and 18 days, indicating a transient inflammatory response without clinical signs of infection." (PMID 42222289, 2026). "Additionally, subgroup analyses by primary infection site showed that MDW consistently outperformed NLR and WBC, and generally outperformed CRP except in soft tissue infections where MDW and CRP performed comparably." (PMID 41598332, 2026). "Although there were no clinical signs of infection or inflammation, baseline inflammation should have been ruled out by assessing CRP and hs‐TnT, as proposed in international guidelines." (PMID 41567753, 2026). "Although the patient did not exhibit any signs or symptoms indicative of an infectious etiology, laboratory tests, including C-reactive protein (CRP) and erythrocyte sedimentation rate (ESR), were conducted as part of the infection screening process, with all results falling within normal limits." (PMID 41585623, 2026). "When comparing the diagnostic performance of NGS and individual biomarkers to infection, NGS was more specific to PJI than synovial CRP (specificity = 0.894, 95% CI: 0.88-0.91), but not PMN or WBC." (PMID 42199553, 2026). "CsA administration resulted in significant elevations of the infection markers PCT and CRP." (PMID 41394124, 2025). "The combination marker CRP–AGR (CAGR), which integrates Alb, Glb, and CRP, has been reported to be useful for diagnosing infections after joint arthroplasty, as it reflects systemic inflammatory responses well and functions as a valuable diagnostic indicator of inflammation." (PMID 40943760, 2025). "However, some pyogenic spondylitis cases are low-inflammatory, in which leukocyte count, CRP, and ESR remain unchanged even during active infection." (PMID 40943760, 2025).